CD4 (CD4 molecule)
Diseases named in the same sentence as CD4 in open-access papers (continued):
Sharing a sentence is not in itself a finding about the gene and the disease.
lymphopenia (continued). "Among the different lymphocyte subsets, evidence exists that CD4+ and NK cells are involved in the lymphopenia associated with anti-Ro or, specifically, with anti-Ro52/TRIM21." (PMID 24294139, 2013). "Recent systemic assessments and clinical analyses have found that CD4+T lymphocytopenia is a strong risk factor for lymphoma development in SS, with the strongest predictor being a lowered CD4+/CD8+ T cell ratio." (PMID 23853604, 2013). "At diagnosis, six patients had lymphopenia with deficiency of CD4 and CD8 T lymphocytes, which was profound in two cases among the 14 patients assessable for these criteria." (PMID 23813854, 2013). "Since leptin is required for lymphopoiesis, leptin receptor-deficient mice have fewer circulating B- and CD4+ T-lymphocytes and are unable to correct irradiation-induced lymphopenia." (PMID 22313574, 2012). "Several other studies also find that lymphopenia is associated with CD4 T cell depletion in severe and/or mild influenza." (PMID 22363665, 2012). "One of the first signs of the immune deficiency that precedes CD4+ lymphopenia in HIV-infected patients is the reduction of IL-2 production and the lack of response to this cytokine." (PMID 23243424, 2012). "The main risk factors for IRIS are severe CD4 lymphopenia and infection at cART initiation, which leads to a dysregulated T-cell response to antigen when severe immunosuppression reverses." (PMID 21955517, 2011). "Immune assessments of DOCK8 mutated AR-HIES patients reveal T cell lymphopenia with low counts of both CD4+ and CD8+ T cells, as well as impaired T cell expansion from activated peripheral blood mononuclear cells in vitro." (PMID 22085750, 2011). "CD4 lymphopenia is known to be an independent risk factor for febrile neutropenia and early death in cancer patients receiving cytotoxic chemotherapy." (PMID 21843362, 2011). "Although old age has been associated with idiopathic CD4+ lymphocytopenia, and the latter has been associated with PML, our patient did not meet the Centers for Disease Control and Prevention criteria for idiopathic CD4+ lymphocytopenia." (PMID 20920200, 2010). "In a multivariate model that included BMI ≥28, medical conditions, CRP, CD4 T cell counts and lymphocytopenia reversion, the variables that were significantly associated with death were BMI ≥28 and delayed lymphocytopenia recovery." (PMID 20513239, 2010). "The association of aging with CD4+ lymphocytopenia and the high JCV seroprevalence in adults should increase awareness about the possible diagnosis of PML in the appropriate clinical and radiographic setting." (PMID 20920200, 2010). "Corticosteroids, lymphopenia and a low CD4+ count in particular, have been identified as risk factors for the development of PCP in adults with AID." (PMID 15488151, 2004). "Previously reported nonsense variants include p.E228*, p.E381*, p.W387*, p.W688*, and p.C812*, with clinical–immunological features converging toward infancy-onset severe infections, near-complete loss of HLA-DR on APCs, marked CD4+ lymphopenia, and low IgG/IgA (IgM variably preserved)." (PMID 41376631, 2025). "The relationship between CD4+T lymphopenia and risk of death in our study suggests that measuring CD4+T lymphocyte counts in critically ill patients may be useful to gauge the risk of infection and overall prognosis." (PMID 39953665, 2025). "Immunophenotyping showed a moderate CD4+ lymphopenia associated with NK cell lymphopenia." (PMID 40756102, 2025). "Univariable logistic regression analysis revealed that age, the number of organs involved, SOFA score, APACHE‐II score, hemoglobin, albumin, NT‐proBNP, CD4+T lymphocytes, and persistent lymphocytopenia were risk factors for mortality in MODS patients (p < 0.1)." (PMID 39953665, 2025). "Similarly, lymphopenia, particularly CD4+ T-cell depletion, has been linked to an increased risk of postoperative infections in HIV-positive patients (Paiardini and Müller-Trutwin, 2013)." (PMID 38988810, 2024).
lymphopenia (continued). "Prophylaxis should continue throughout the period of immunosuppression and CD4+ lymphopenia, particularly PWH who may be at a heightened risk." (PMID 39459894, 2024). "Furthermore, bendamustine had a complex immunosuppression profile and infection risk for the patient, such as myelosuppression, including lymphopenia and a low CD4+ T count, and hypogammaglobulinemia." (PMID 38541221, 2024). "Through a case of idiopathic CD4+ lymphopenia, we uncovered a previously unrecognized role of the mitochondrial chaperon protein Tumour Necrosis Factor-Receptor Associated Protein 1 (TRAP1) in CD4+ lymphocytopenia and in the mechanism of PjP immunopathogenesis." (PMID 39224595, 2024). "Moreover, the ART-mediated reversal of CD4 lymphopenia in advanced HIV/TB patients was associated with incident lung involvement in one of the studies." (PMID 38793546, 2024). "Bendamustine causes prolonged lymphopenia and depletion of CD4-positive T cells." (PMID 38803441, 2024). "Interestingly, CD4+ lymphopenia in PB has been associated with resistance to conventional immunosuppressant such as corticosteroids and methotrexate but responsive to treatment with TNF-α inhibitors." (PMID 37161980, 2023). "Moreover, in some patients, CD4+ lymphopenia lasts for several months, increasing the risk of infection and other complications." (PMID 36875084, 2023). "Moreover, coinfections caused severe lymphopenia in peripheral blood, resulting in reduced total IgG, neutralizing antibody titers, and CD4+ T cell responses against each virus." (PMID 35107382, 2022). "Although peripheral lymphocytopenia, especially a low CD4+ T-cell count, is a recognized risk factor for HIV-PJP, the peripheral lymphocyte percentage, absolute lymphocyte count, and subtype features are variable among the different studies of non-HIV-PJP patients administered corticosteroids." (PMID 36552932, 2022). "Previous studies showed that a prominent decline in lymphocyte (specifically CD4+ T lymphocytes) counts may be observed in sepsis, and sepsis-associated lymphopenia is significantly associated with patients who die from sepsis." (PMID 36453923, 2022). "Persistent IFN stimulation induces apoptosis of CD4+ T lymphocytes and causes lymphopenia." (PMID 35625619, 2022). "Further, naïve tumor-specific CD4+ T cells can naturally differentiate into Th1 cytotoxic T cells in vivo and cause the regression of established tumors in hosts with lymphopenia, supporting the potential for the use of tumor-reactive CD4+ T cells in cancer immunotherapy." (PMID 35784297, 2022). "However, the results showed that CD4+ T lymphopenia was significantly associated with poor survival in local/loco-regional disease, but not in metastatic patients." (PMID 35546670, 2022). "In a mouse model of cancer cachexia, the adoptive transfer of CD4+CD44Low naïve T-cells reduces muscle atrophy, muscle protein and DNA loss, even when inoculated after the onset of cachexia, associated with a protection from CD4+ T-cell lymphopenia." (PMID 36158184, 2022). "The poor prognosis associated with CD4 lymphopenia is widely documented in many cancers." (PMID 35546670, 2022). "This cut-off achieves a 74% sensitivity and 81% specificity, supporting the hypothesis that CD4+ T lymphopenia may predispose to poor AAD surgical outcomes." (PMID 34869652, 2021). "Naïve CD4+ lymphopenia is one potential component of the splenomegaly-associated leukopenia." (PMID 35062255, 2021). "We cannot hypothesize whether C. violaceum is the cause of or the effect of CD4 + lymphopenia in this Malaysian CGD series." (PMID 34001231, 2021). "In a murine PICS model, lymphopenia was depicted in a quantitative loss of CD4+ and CD8+ T cells." (PMID 34285925, 2021). "Bone marrow dysfunction may be responsible for other hematologic defects associated with GS including lymphocytopenia, CD4 lymphopenia, neutropenia and eosinopenia." (PMID 35095915, 2021).
lymphopenia (continued). "Chronic active HCV infection has been associated with naïve CD4+ lymphopenia, particularly in the CD4+CD31+ T cell subset, and enhanced death of all peripheral T cell subsets could be one underlying mechanism." (PMID 35062255, 2021). "SARS-CoV infection leads to lymphopenia and strongly reduced peripheral T cell levels, with low CD4+ and CD8+ T cell counts associated with adverse outcome, and a rapid and dramatic restoration of peripheral T cell subsets in the periphery of recovering patients." (PMID 33013871, 2020). "Grade 3/4 AEs of lymphopenia and decreased CD4 lymphocytes were also attributed to DMF as it may cause lymphopenia." (PMID 32642720, 2020). "Since lymphopenia is a hallmark of sepsis and differentially affects CD4 T cell precursor populations, a reduction in precursor numbers is one possibility for the decreased number of autoantigen-specific CD4 T cells in the iLN at the day 7 priming timepoint." (PMID 33191915, 2020). "It remains to be determined whether the hypogammaglobulinemia, the CD4-lymphopenia or the combination of both constitute the major risk factor for HEV persistence following RTX-containing treatment regimens." (PMID 31947836, 2020). "Moreover, CD4+ T cell lymphopenia in patients with Sjögren's autoimmune syndrome or idiopathic CD4+ lymphopenia is associated with an increased risk of cancer." (PMID 30922400, 2019). "Our findings suggest that the lymphopenia, especially decreased CD4+ T cell counts, may be associated with presence of CMV disease among patients with SLE." (PMID 31574798, 2019). "Irrespectively of the mechanisms underlying CD4 lymphopenia, we suggest that the presence of CD4 lymphopenia in the context of ALPS-FAS may have clinical implications for its diagnosis, natural history and treatment." (PMID 31191551, 2019). "In HIV-uninfected patients with durable CD4+ T cell deficiency (deemed idiopathic CD4+ lymphopenia), similar ILC deficiencies in blood were observed, collectively identifying determinants of ILC homeostasis in primates and potential mechanisms underlying their depletion in HIV/SIV infection." (PMID 30262807, 2018). "CD4-Cre excises a floxed allele with greater than 99% efficiency; therefore, the rare group of <1% of cells that escaped Zfx deletion initiated homeostatic proliferation in response to lymphopenia secondary to loss of Zfx-deficient T cells." (PMID 30022979, 2018). "The lymphopenia upon specific deletion of Atg3, Atg5, Atg7, Atg16l1, or Vps34 in T cells has been demonstrated to be associated with increased percentages of activation/memory-like T cells within both the CD4+ and CD8+ compartments." (PMID 28572806, 2017). "Vaccination in the absence of CD4+ T cells induces Tc17 cells that confer resistance against lethal experimental fungal pneumonia, a feature that can be translated to immune-compromised individuals with CD4+ T cell lymphopenia that are susceptible to opportunistic fungal infection." (PMID 28542595, 2017). "Interestingly, Tpl2 deficiency enhanced the lymphopenia-induced accumulation of transferred effector CD4 T cells in this colitis model." (PMID 25781948, 2015). "Other studies have reported CID with CD4 lymphopenia in patients bearing hypomorphic mutations in genes which are typically associated with severe combined immunodeficiency (SCID) phenotype, such as RAG1, which is known to cause SCID when mutated in amorphic manner." (PMID 25205547, 2014).
lymphopenia (continued). "Because of the recurrent infectious episodes primary immunodeficiency was suspected and an immunological work-up was initiated which revealed CID with CD4 lymphopenia on multiple occasions, IgG2-IgG4-subclass deficiency, and selective antibody deficiency against bacterial polysaccharide antigens." (PMID 25205547, 2014). "It is conceivable that other patients with primary CD4 lymphopenia may, in a similar fashion, bear hypomorphic mutations and/or somatic chimerism in other genes which are usually associated with SCID phenotypes." (PMID 25205547, 2014). "However, it appears likely that other subgroups of patients with CD4 lymphopenia are caused by novel nosological entities involved in T-cell homeostasis." (PMID 25205547, 2014). "For memory CD4+ T-cells, we found that, although proliferation rates were associated with viral load and CD4 lymphopenia, the strongest association was with immune activation (HLA-DR/CD38 coexpression), although it should be noted that no markedly lymphopenic subjects were recruited." (PMID 24803534, 2014). "Modeling was performed to estimate the sensitivity, specificity and positive and negative likelihood ratios for various combinations of risk factors (fever, oral candidiasis, lymphadenopathy, CD4 lymphopenia, anemia, thrombocytopenia) for confirmed/probable TB and for NTS infection." (PMID 22761767, 2012). "Lymphopenia is caused by direct replication of the virus in CD4+ lymphocytes." (PMID 23202500, 2012). "Several investigators observed increased serum levels of IL-7 in HIV-1-infected patients characterized by severe CD4+ lymphopenia, and showed direct correlation between IL-7 serum concentration and viral load, loss of CD4+ T cells, and alteration of B cell subsets." (PMID 22474482, 2012). "Interestingly, the association of CD4 lymphopenia in primary immunodeficiency seems to be stronger with granulomatous inflammatory disease than AI cytopenias." (PMID 22826712, 2012). "However, CMV-seropositivity showed an add-on effect on CD4+ Tnaive lymphopenia and was associated with the development of terminally differentiated effector-memory T cells in both the CD4+ and CD8+ compartment." (PMID 21214947, 2011). "Further, chronic leishmanial infections cause CD4 lymphopenia and low CD4/CD8 ratio." (PMID 22011565, 2011). "Also, there seems to be an association with lymphopenia, an inverted CD4/CD8 ratio and decreased T-cell proliferation in response to mitogens and antigens." (PMID 21143835, 2010). "The most plausible variables that may impact outcome in our patients include hypogammaglobulinemia, qualitative and quantitative B- and T-cell deficiencies, CD4 + lymphopenia, innate immune dysfunction, and neutropenia, all resulting from haematological malignancy itself and respective treatment." (PMID 38388854, 2024). "Although CVID diagnostic criteria exclude severe CD4+ T lymphocytopenia, the use of prolonged therapies such as corticosteroids is common as a first-line treatment for inflammatory manifestations of the disease, and may induce a temporary decrease of T-cells subpopulations as consequence." (PMID 34108596, 2021). "This hypothesis finds support in the results here obtained in Jurkat and CD4+ T cells and might provide a rationale for Gsnor‐null mice lymphopenia, which is, indeed, associated with a decreased number of both T and B cells and with an increased rate of apoptosis of CD4+ thymocytes." (PMID 33245190, 2021). "Previous studies indicated that lymphopenia may occur early in the course of sepsis and that decreases of specific lymphocyte subsets, including CD4 T cells, may help identify fragile patients at higher risk of disease progression among those hospitalized due to infection." (PMID 34372784, 2021).
lymphopenia (continued). "In addition, in PLE, a high NLR can also be determined by the loss of CD4+ T cells through retrograde drainage of the lymphatic system in the intestinal lumen and the lymphopenia in lymphangiectasia is thought to be due to loss of lymphocytes through rupture of lacteals." (PMID 32971945, 2020). "Therefore, we speculated that CD4 lymphopenia in ALPS-FAS could be caused by (a) decreased thymic output, (b) reduced homeostatic proliferation in paracortical T cell areas engulfed with DNT-cells, or (c) autoimmune peripheral destruction." (PMID 31191551, 2019). "PJP is rarely described in patients with idiopathic CD4+ lymphocytopenia (ICL), a rare T-cell deficiency of unknown origin with persistently low levels of CD4+ T-cells (<300 μl−1 or <20 % of total lymphocytes) but repeated negative human immunodeficiency virus (HIV) tests." (PMID 28663813, 2014). "One straightforward explanation for the loss of naive CD4+ T cells may be their conversion to memory-like cells as a homeostatic response to severe lymphopenia, as described in mouse models of T cell depletion and in patients undergoing myeloablative therapies." (PMID 23383227, 2013). "In some cats, lymphopenia may be characterized by preferential loss of CD4+ helper T cells, resulting in an inverted CD4/CD8 ratio (as typically seen in FIV infection), but more commonly, substantial losses of helper cells and cytotoxic suppressor cells (CD8+ cells) occur." (PMID 23202500, 2012). "Cortisol-induced lymphopenia leads to a decrease in both CD4+ helper and CD8+ cytotoxic T cells, with studies showing reductions in circulating during the acute phase of RWL." (PMID 41516380, 2026). "CD4+ T cell lymphopenia and humoral dysfunction were consistent, while total lymphocyte counts were variable." (PMID 42099591, 2026). "Hallmark laboratory features included refractory lactic acidosis, extreme hyperferritinemia, markedly elevated lactate dehydrogenase, and profound CD4+ lymphopenia." (PMID 41847713, 2026). "Subsequent immunologic evaluation demonstrated persistent isolated CD4 lymphopenia on serial testing, establishing a diagnosis of ICL." (PMID 42028536, 2026). "Lymphocyte subsets in this case did show T-cell lymphopenia, however, curiously affecting CD4+ counts more than CD8+ counts." (PMID 41230284, 2025). "In our study, the FTN-exposed rats exhibited an obvious lymphocytopenia accompanied by a substantial downregulation of CD4, CD3, CD20, and CD56 but upregulation of CD8." (PMID 39981186, 2025). "Severe CD4+ lymphopenia (146/μl) was detected in a patient with confirmed HIV infection by serology." (PMID 40656199, 2025). "The Mo-AMs establish a proinflammatory state in lungs, attracting other innate and adaptive immune cells, including natural killer cells (NK), CD4+, CD8+ T cells and B cells from the periphery and causing lymphopenia." (PMID 40963624, 2025). "At the same time, lymphopenia reflects the widespread phenomenon of apoptosis of immune cells in sepsis, especially the significant depletion of CD4 + T cells and B cells." (PMID 41001389, 2025). "Docetaxel is known to induce transient but profound lymphopenia, particularly affecting CD4+ T‐cells, which play a central role in host defence against pneumocystis." (PMID 41378364, 2025). "We found B and NK cell lymphopenia with a significant increase of CD4 + and CD8+ T lymphocytes, and the B cell responses have been shown downregulated in APS-1 patients." (PMID 38605470, 2025). "Common laboratory trends included mild anemia, lymphopenia (including CD4 counts), and mildly elevated mean lactate dehydrogenase." (PMID 41251369, 2025). "There are no major immunological limitations for the development of an adequate response (i.e., severe hypogammaglobulinemia, severe CD19+ or CD4+ lymphocytopenia)." (PMID 40333279, 2025).